CD80 (CD80 molecule)
Diseases named in the same sentence as CD80 in open-access papers (continued):
Sharing a sentence is not in itself a finding about the gene and the disease.
tumor (continued). "Moreover, tumor cells often show a downregulation of costimulatory CD80/CD86 molecules, which hampers T cells’ activation and contributes to low T-cell function." (PMID 35335881, 2022). "Interestingly, OSCC with high F3 expressed higher levels of the key immune checkpoint molecules CD274/PD-L1, PDCD1LG2/PD-L2 and CD80, especially in tumor dendritic cells." (PMID 35053621, 2022). "By inhibiting the interaction between the immune checkpoints expressed on T cells, such as PD-1 and CTLA-4 and their ligands (PD-L1 and CD80/86) expressed by tumor cells/antigen-presenting cells, ICIs induce the activation of T effector cells targeting tumor cells." (PMID 35372076, 2022). "The authors showed that the silencing of CD80 by RNA interference led to the loss of tumorigenicity of CT26 tumor cells in immunocompetent mice, but not in immunodeficient mice." (PMID 35572581, 2022). "Indeed, co-culture of DCs with ORFV NA1/11-infected tumor cells engulfed more tumor cells than with uninfected tumor cells, and DCs exhibited high levels of CD80, CD86 and MHC I expression." (PMID 35959371, 2022). "Thus, the co-expression of CD80 and PD-L1 in cis on tumor cells prevents PD-L1 from the tumor to deliver co-inhibitory signals in trans to T cells." (PMID 35795681, 2022). "In addition, CD40L expression also increased in vivo cytotoxicity and enhanced anti-tumor immunity through up-regulation of CD80 (B7-1), CD86 (B7-2), and Fas receptor on tumor cells." (PMID 35199207, 2022). "Therefore, the spleens of tumor-bearing mice after different therapies were collected and measured by flow cytometry to evaluate the variation of mature DCs (CD11c+, CD80+, CD86+)." (PMID 35812418, 2022). "Interactions between DC-expressing molecules (major histocompatibility complex (MHC) proteins loaded with tumor antigens and costimulatory molecules (CD80, CD86)) with T cell-expressing receptor (TCR), coreceptors (CD4, CD8), and CD28 are necessary for optimal activation of T lymphocytes." (PMID 35757015, 2022). "One might speculate that CD80 directs MSC toward PD-L1–expressing tumor or suppressive myeloid cells, leading to reduced T cell activation." (PMID 36073543, 2022). "In our case, hypotheses are made based on our current understanding of the tumor-immune system, which is constantly updated by new experimental data, such as the cis interaction between CD80 and PD-L1." (PMID 35856032, 2022). "We did note a slight increase in proportion of cells co-expressing CD40 and CD80 in the converted tumor-migratory CD11b+ DCs, although the overall number of these cells migrating was still significantly reduced in radiation-treated animals compared with untreated controls." (PMID 35487695, 2022). "Evidence to date suggests that concomitant Fc-mediated depletion of Tregs alongside blockading CD80/86-CTLA-4 interactions may be necessary for maximal anti-tumor activity." (PMID 35326731, 2022). "Therefore, increased presence of tumor-infiltrated CD80 and CD86-expressing DCs ensures optimal and successful generation of effector, tumoricidal T cells which would, upon activation, infiltrate the tumor tissue to eliminate cancer cells." (PMID 35757015, 2022). "CD80 on the tumor is considered an essential part of antitumor CTL effector function." (PMID 36032099, 2022). "Tumor cells, tumor infiltrating lymphocytes and tumor associated myeloid cells express inhibitory PD-L1/CTLA4 ligands to engage PD-1 receptors on cytotoxic T cells and CD80/86 receptors on myeloid cells, effectively blocking immune activation against the tumor cells." (PMID 35967449, 2022). "Many tumors are highly infiltrated by CD163+ M2c pro-tumorigenic macrophages which actively suppress anti-tumor immune responses by: upregulation of PD-L1, downregulation of CD80/86, and release immunosuppressive cytokines and metabolism-altering factors like IDO and NO13,34,35." (PMID 35379805, 2022).
tumor (continued). "Notably, infiltrating immune and tumor cells present immunosuppressive molecules, such as programmed death-ligand 1 (PD-L1) and CD80/CD86." (PMID 33406733, 2021). "However, the interaction of mouse CTLA-4 with CD80 has been reported to outcompete the tumor-suppressive CD80 and PD-L1 in cis interaction." (PMID 33923750, 2021). "Furthermore, irradiation increases the expression of the T cell costimulatory molecule CD80 on a variety of tumor cells, which increases tumor cell immunogenicity." (PMID 33562450, 2021). "Furthermore, Treg hamper anti-tumor immunity via the interaction of CTLA-4 with the co-stimulatory receptors CD80 and CD86, which are expressed by APC-like DC, resulting in the inhibition of their T cell stimulatory capacity." (PMID 33430105, 2021). "We, therefore, introduced a clinically relevant mouse tumor model with deactivated CD80." (PMID 33923750, 2021). "Taken together, these results suggested that CTLA4-T cells confer strong anti-tumor activities and could specifically suppress CD80/CD86-expressing tumors in vivo." (PMID 33868277, 2021). "Tumor-infiltrating B-cell can expedite the tumor antigens present to stimulate the function of T lymphocytes via upregulating costimulatory molecules (such as CD80/86) and HLA-II." (PMID 34820451, 2021). "Additionally, recurrent HCC showed a higher proportion of PD-L1+ malignant cells than primary HCC, and competitive binding of PD-L1 to CD80 inhibited antigen presentation which further led to compromised anti-tumor immunity." (PMID 35117990, 2021). "As CD80 expression on tumor cells can influence their immunogenicity, we sought to determine whether CD80 expression on TC-1 cells affects tumor growth, the tumor microenvironment, and the sensitivity to immune checkpoint blockade." (PMID 33923750, 2021). "Finally, the development of the tumor-cell-targeted CD80 blockade should be assessed as a novel immunotherapeutic approach." (PMID 33923750, 2021). "CTLA-4+ tumor-infiltrating Tregs could also contribute to tumor immune evasion by suppressing antitumor immunity and downregulating CD80/86 expression on APCs." (PMID 34868991, 2021). "It has been previously reported that the expression level of CD80 may regulate the pro-/anti-oncogenic role of CD80 on tumor cells." (PMID 33923750, 2021). "Notably, tumor growth has been retarded upon CD80 knockout or antibody-mediated blockade of either CD80 or CTLA-4." (PMID 33430105, 2021). "Similarly, PIR-B or PD-L1 inhibition reduced the proportion of CD206+ and CD163+ TAMs but elevated that of CD86+ and CD80+ TAMs in tumor tissues with the most obvious alteration in the combined blockade group." (PMID 33537094, 2021). "They further demonstrated that CD80 is necessary for the tumor-initiating stem cells to endure immune attack and CD80 could dampen the activity of cytotoxic T cells through directly engaging with CTLA4." (PMID 34722635, 2021). "Furthermore, GRP78 heterozygous tumor-bearing mice displayed increased CD68/CD80 co-localization when compared with wild-type tumors, suggesting increased infiltration of the tumors by M1-like macrophages." (PMID 34943954, 2021). "The anti-inflammatory CD163+ macrophages (M2-like) were more prevalent in advanced tumor stage and exclusively located in invasive tumor front, whereas the CD80+ macrophages (M1-like) were predominant in less invasive tumors and predominantly distributed in tumor-adjacent normal mucosa." (PMID 33763066, 2021). "Paradoxically, anti-PD-L1 administered as a single therapy may enhance CTLA-4/CD80-mediated immunosuppression in some patients due to the disruption of the tumor-suppressive CD80 and PD-L1 in cis interaction." (PMID 33923750, 2021). "DC maturation in the TME can be promoted by HMGB1 stimulated by preoperative chemoradiotherapy and is accompanied by surface molecule (CD80, CD86, CD208, and LAMP3) expression with anti-tumor functions of tumor-associated antigen presentation, which facilitates effective CD8+ T cell activation." (PMID 33995371, 2021).
tumor (continued). "Conditioned media from GRP78-silenced breast cancer cells increased expression of tumor-attacking M1 macrophages (with CD80+ marker) and reduced the M2 marker, Arg-1, while conditioned media from control cells showed elevated macrophage CD206+ (an M2-like macrophage marker)." (PMID 34943954, 2021). "TAMs are also broken down into subsets based on polarization to the M1 macrophage-like phenotype (pro-inflammatory/anti-tumor) CD68+ CD80/86+ CD11c+ iNOS+ and the M2 macrophage-like phenotype (pro-tumor) CD163+ CD204+ CD206+ Arg1+, with M2-like TAMs being the most immunosuppressive." (PMID 34136405, 2021). "Further, PANVAC is a therapeutic poxviral vaccine containing the genes for the tumor-associated antigens MUC-1 and carcinoembryonic antigen (CEA), as well as immunostimulatory genes CD80, intracellular adhesion molecule-1 (ICAM1), and leukocyte function-associated antigen-3 (LFA3)." (PMID 33562450, 2021). "Previously, it has been shown that CD80 silencing, as well as overexpression, in tumor cells could inhibit their oncogenicity." (PMID 33923750, 2021). "Our study implies that CD80 expression on tumor cells should be evaluated further as a possible predictive marker that may assist clinicians in the selection of cancer patients who may be suitable for CTLA-4 blockade cancer therapy." (PMID 33923750, 2021). "We found that C190 expression regulated immune-checkpoint-related binding partners including CD80 and PD-L1, which may have an influence on the immune evasion in the tumor microenvironment." (PMID 35008490, 2021). "Accordingly, blocking the binding of CTLA4 and CD80 could specifically eliminate these tumor-initiating stem cells and inhibit tumor relapse after immunotherapy." (PMID 34722635, 2021). "The M1 macrophages produce pro-inflammatory factors (TNF-α, IL-1β, and iNOS), chemokines (CXCL10, CXCL11, and CCL2), antigen-presenting molecules such as MHCII, costimulatory molecules (CD86 and CD80), and antigen-treated peptidases, which play an anti-tumor role in cancer." (PMID 34034714, 2021). "This means that CD80 is functionally activated and responds to local primary tumor growth." (PMID 33669410, 2021). "Some studies have shown that tumor-initiating stem cells inhibit cytotoxic T cell responses via the surface molecule of CD80, which suggests that tumor-initiating stem cells could be essential to activating immune checkpoint pathways." (PMID 34900983, 2021). "Also, it has been shown that A20 tumor cells show altered expression of the costimulatory CD80 and are a potent source of IL-10 secretion, suggesting an important immunosuppressive status that accompanies A20 cell establishment." (PMID 34413847, 2021). "Furthermore, i.t. injection of Sirpα−/− macrophages led to an increase in the expression of immunogenic antigen presentation machinery (MHC-I/II, CD80/86, and OX40L) on endogenous WT tumor-associated macrophages." (PMID 34050181, 2021). "Reduced CTLA4 expression on tumor-infiltrating T cells might permit increased expression of CD80/CD86 on Hodgkin-Reed-Sternberg cells, thereby increasing T cell proliferation and modifying the tumor environment." (PMID 33876323, 2021). "Therefore, it is necessary to dissect the functions contributed by the crosstalk between PD-L1/PD-1 and PD-L1/CD80 pathways in tumor microenvironment to explore new opportunities for tumor treatment." (PMID 33178688, 2020). "CD80 expression on tumor stem cells directly decreases T-cell activity upon engaging with CTLA-4." (PMID 32380703, 2020). "B cells (CD19+) were found infiltrating some CRC tumours, but the levels of B cells were however slightly lower in tumour compared to adjacent normal tissues, with slightly increased expression of CD80 and decreased expression of the antigen presenting molecule human leukocyte antigen-DR (HLA-DR)." (PMID 33228141, 2020).
tumor (continued). "Compared with unpulsed group, tumor lysates of RenCa, 4 T1 and CT26 caused remarkable up-regulation of CD80, CD86 and MHC-II expression in DCs, which suggested the maturation of DCs could induced by tumor cells lystates." (PMID 32641056, 2020). "Moreover, circulating pDCs exhibited an altered response when compared to HD (% and/or MFI), while tumor‐infiltrating pDCs still upregulated CD80 and CD40 (MFI) upon R848 stimulation." (PMID 33282290, 2020). "Thus, Flt3L and CD80 represent targets for adjuvant interventions to enhance T cell-mediated anti-tumor immune responses." (PMID 32161596, 2020). "Therefore, CD80-Fc presents as a potentially “off-the-shelf” approach for enhancing anti-tumor DNA vaccination." (PMID 32161596, 2020). "Among genes encoding costimulatory molecules, CD70 and CD80 were similarly expressed by FL and normal GC B cells, while CD86 was significantly overexpressed in tumor cells (p = 0.004), and could contribute to the activation of Tfh after binding to CD28." (PMID 33028033, 2020). "Further investigations are needed to delineate the role of (a) cellular components (regulatory cells, natural killer cells, etc.)that include costimulatory versus coinhibitory molecules, (b) molecular components (CD28, CD86, CD80, etc.), and (c) cellular mechanisms involved in anti-tumor response." (PMID 32326142, 2020). "Interestingly, they activated NK cells, exhibited cytotoxicity against cancer cells by inducing ADCC and inhibited tumor cell growth by affecting CTLA-4 downstream pathways in a similar fashion to CD-80 and CD-86 ligands and differently from Ipilimumab." (PMID 32781690, 2020). "Moreover, an association between higher CD80+/CD163+ cell ratio at the tumor invasive front and improved survival was found, as well as a protective role of CD80+ macrophages in preventing tumor relapse." (PMID 32650452, 2020). "The peptide also blocks the CD80/PD-L1 interaction, which may further enhance the immune response of tumor-infiltrating T cells." (PMID 31640814, 2019). "CTLA-4 integrates with the costimulatory molecules CD80 (B7-1) and CD86 (B7-2) that express on the surfaces of APCs, while PD-L1 is expressed on a wide variety of cell types, including tumor-associated fibroblasts, tumor cells, APCs, etc.." (PMID 30774597, 2019). "We found that tumour-cell debris after HMME/R837@Lip-augmented SDT could significantly promote DC maturation (CD80+CD86+ DCs) in comparison with HMME@Lip-assisted SDT." (PMID 31048681, 2019). "In addition, tumor expression of CD80 also enhances CTL effector functions and facilitates tumor immunity by inhibiting PDL1-mediated immune suppression." (PMID 31072360, 2019). "In an implantable murine model of metastatic osteosarcoma, treatment with anti-PD-L1 antibody resulted in downregulation of PD-L1 expression and upregulation of CD80/CD86 expression on tumor cells, as well as upregulation of CTLA-4 on tumor infiltrating CD8+ T cells." (PMID 31847387, 2019). "Also, most primary tumor cells lack expression of costimulatory molecules such as CD80, CD86, and ICOSL, and T cell anti-tumor responses can be compromised by lack of costimulation." (PMID 32038630, 2019). "The CD80/PD-L1 interaction specifically restrains T cell activation, and blockade of the interaction could enhance the anti-tumor activity of the T cells." (PMID 31640814, 2019). "T-reg-derived IL-10 alters the myeloid compartment in the TME, indirectly providing regulation of T-cell-mediated anti-tumor immune responses through upregulation of T-cell stimulatory molecules such as major histocompatibility complex class II and CD80 on intra-tumor DCs." (PMID 31547627, 2019). "We found no striking differences in expression of known co-inhibitory or co-stimulatory molecules such as PD-L1, CD80/86, or 4-1BB that might explain the differential tumor cell sensitivity to CD20xCD3 bsAb." (PMID 31882897, 2019).
tumor (continued). "Similarly, tumor cell downregulation of costimulatory molecules including CD40, CD80, CD86, and ICAM1 have been observed and associated with the rapid progression of various cancers as reviewed in." (PMID 30740111, 2018). "This hypothesis is supported from our experiments using CD80+/CD86+ Raji tumor models, which provides comparable CD28 costimulation to both CAR-T and AbTCR-T cells." (PMID 30479831, 2018). "In addition, transgenic expression of CD80 has been shown to induce tumor regression in xenograft experiments and human clinical trials." (PMID 30123257, 2018). "Here, we have shown that G3 CAR T-cells, cocultured with CD32-80-137L-EGFRVIIIΔ654 aAPC cells (CD32, CD80, 41BBL, and EGFRvIII) can survive at day 90, provide enhanced anti-tumor activity, and able to destroy tumor stroma with single treatment of 25,000 CAR T-cells." (PMID 29975720, 2018). "Anti-CTLA-4 antibodies enhance tumor-specific immunity through a variety of mechanisms including: blockade of CD80 or CD86 binding to CTLA-4, repressing regulatory T cell function and selective elimination of intratumoral regulatory T cells via an Fcγ receptor-dependent mechanism." (PMID 29617360, 2018). "In contrast, IL-2/CD40 induced reduced MHC-I and CD80 in young, but not elderly, tumor-associated CD11c+ cells." (PMID 30560130, 2018). "In view of these interesting observations from this and other studies, it is plausible that CD274 may work with its related molecule, e.g., CD80, in triggering acute phase liver graft injury and post-transplant tumor recurrence." (PMID 29642405, 2018). "However, only SN of the irradiated tumor cells induced a significant higher increase in the percentage of migrated mDCs showing enhanced expression of the activation markers CD80 and CD86 compared to mock treated and medium controls." (PMID 28337197, 2017). "To investigate whether CD80 might be negatively associated with tumor regression, we transfected 4T1.2/HER2 cells with pCEP4-CD80 and selected a tumor cell clone expressing CD80 for use in a tumor cell challenge study." (PMID 28460461, 2017). "Ligand CD80 reacts with the CTLA-4 receptors present on the tumor cells to induce apoptosis." (PMID 27843708, 2016). "Additionally, we found that, compared to the tumor specific E6/E7 peptide vaccine, total tumor lysate induced higher expression of CD80 and CD40 on DCs that induced increased levels of IFNγ production upon interaction with host lymphocytes." (PMID 27223090, 2016). "IFN-γ has been shown to induce apoptosis in cervical tumour cells and results in increased expression of HLA class I and HLA class II molecules, which significantly enhance the recognition and lysis of tumour cells by specific cytotoxic T lymphocytes (CTLs) activated by CD80-expressing tumour cells." (PMID 27293315, 2016). "The recombinant virus used in fowlpox-TRICOM expresses three costimulatory transgenes, B7.1 (CD80), Intercellular Adhesion Molecule 1 (ICAM-1), and lymphocyte function-associated antigen 3 (LFA-3), plus one or more tumor-associated antigens, such as Carcinoembryonic antigen (CEA) and MUC-1." (PMID 27669306, 2016). "This identified some densely packed tumor cells that detected low level of CD80 expression." (PMID 26107716, 2015). "An alternative explanation is that PD-L1 mAb treatment may be altering the microenvironment towards a T cell suppressive state, however increases in CD80/86 expression on the tumor cells after PD-L1 treatment suggest direct K7M2 TIL inhibition." (PMID 25992292, 2015). "Along with the uptake of tumor-associated antigens and presentation in the context of MHC molecules, professional APCs are further required to provide lymphocyte costimulation, such as through expression of the B7 molecules (CD80 and CD86) or CD40." (PMID 26483791, 2015). "Moreover, GB treatment of tumor-bearing mice induced up-regulation of CD80, MHC class I and II expression in spleen and tumor drLN DCs." (PMID 26090808, 2015).